LINC01348 (long independently transcribed non-coding RNA 1348)
Gene: Long non-coding RNA gene on chromosome 1 (235,054,610 to 235,074,378, reverse strand). Ensembl gene ENSG00000280587.
Diseases named in the same sentence as LINC01348 in open-access papers:
LINC01348 is named in the same sentence as 2 diseases in open-access papers, as found by Europe PMC text mining. Sharing a sentence is not in itself a finding about the gene and the disease. The quoted sentences say what the papers report.
hepatocellular carcinoma (1 paper, 2022). A malignant tumor that arises from hepatocytes. "BDE-47 induced the expression of SNHG17 and LINC01348, respectively, an oncogene and a tumor suppressor in hepatocellular carcinoma (HCC)." (PMID 36430946, 2022).
LINC01348 also shares sentences with these, for which no sentence is quoted: tumor (1 paper).